KLF4 (KLF transcription factor 4)
Diseases named in the same sentence as KLF4 in open-access papers (continued):
Sharing a sentence is not in itself a finding about the gene and the disease.
tumor (continued). "The activity of KLF4 as a tumor suppressor has been suggested in different types of cancers in which its expression is downregulated such as leukemia, gastric, colorectal, esophageal, bladder and non-small-cell lung carcinomas." (PMID 25181544, 2014). "In such a case, elevated KLF4 expression in surrounding stromal cells, despite low KLF4 expression in the tumor cell itself, would skew our analysis, leading us to incorrectly conclude that KLF4 expression in tumors is elevated." (PMID 25060774, 2014). "Results showed that the tumor weights and growth rates of mice injected with Klf4-overexpressed or HDAC1-inhibited cells were significantly lower than those of the control group." (PMID 25341045, 2014). "Our data demonstrate that KLF4 inhibits cell proliferation, migration, and invasion, hence it functions as a tumor suppressor in both SKOV3 and OVCAR3 cells." (PMID 25137052, 2014). "In contrast to our results, another study using breast CSCs suggested that by negatively modulating KLF4 levels, miR-7 functions as a tumor suppressor." (PMID 25181544, 2014). "According to the fact that KLF4 has a tumor suppressor function in epithelial cells, here we show that down regulation of KLF4 protein by miR-7 overexpression in skin and lung epithelial cells promoted cell proliferation." (PMID 25181544, 2014). "Klf4 expression can regulate tumor growth in mouse xenograft studies and tumor number in APC mediated tumorigenesis." (PMID 24997475, 2014). "Our data suggests that KLF4 mRNA expression level in both normal and tumor tissue is a potential prognostic marker in patients with CRC." (PMID 25060774, 2014). "We conclude that the promoter hypermethylation of KLF4 inactivates its function as a tumor suppressor in cervical carcinogenesis." (PMID 24551169, 2014). "The role of KLF4 has been extensively examined in several types of cancer and has been found to function as a tumor suppressor or an oncoprotein in a tissue type-dependent manner." (PMID 24897024, 2014). "We also demonstrate that overexpression of miR-7 in epithelial cells promotes tumor formation in nude mice and that KLF4 protein levels are significantly downregulated in the formed tumors." (PMID 25181544, 2014). "In our pervious study, the KLF4 gene was found to be inactivated and to function as a tumor suppressor in cervical carcinogenesis." (PMID 24551169, 2014). "In conclusion, the current study indicated that KLF4 potentially serves as a tumor suppressor in HCC development and progression." (PMID 24897024, 2014). "The KLF4 gene acts as both an oncogene and a tumor suppressor, depending on its genetic and cellular contexts." (PMID 25037230, 2014). "KLF4 acts as cell cycle regulator and functions as a tumor suppressor through its ability to induce p21CIP and suppress SP1 expression." (PMID 25037230, 2014). "Similar to the findings in vitro, the activation of Klf4 in Py2T cells led to significantly decreased rates of apoptosis in Klf4-activated tumors, while tumor cell proliferation was only moderately increased." (PMID 23451207, 2013). "KLF4 functions either as a tumor suppressor or an oncogene depending on different cellular contexts." (PMID 23861801, 2013). "We demonstrated that positive expression of Klf4 was significantly correlated with vascular invasion, poor tumor differentiation, short post-operative recurrence time and a poor prognosis." (PMID 23599755, 2013). "KLF4 functions as a tumor suppressor in several tissues in various cancers, such as colorectal, prostate, hepatic, gastric, and intestinal cancers." (PMID 23861801, 2013). "A significant decrease in KLF4 expression was observed in ccRCC tumor tissues compared with that in patient-matched adjacent normal tissues." (PMID 23861801, 2013). "Our observations propose a critical transcriptional role of Klf4 in the regulation of primary tumor growth, EMT and metastasis." (PMID 23451207, 2013).
tumor (continued). "On the other hand, another study has revealed a tumor suppressive function of KLF4 in a KLF4/CreERTM mouse model." (PMID 23861801, 2013). "Our previous study suggested that tumor-suppressive Klf4 undergoes mesenchymal epithelial transition (MET) and reduces the capability for migration, invasion, and lung metastasis in mesenchymal-like cells." (PMID 24196357, 2013). "Here, we investigated the epigenetic regulation of pluripotency-associated genes NANOG, OCT4, c-MYC, KLF4, and SOX2, and their correlation with gene expression in cancer cell lines and primary tumor samples." (PMID 24023739, 2013). "With regard to tumor differentiation, a significant correlation was identified between Klf4 expression and poor tumor differentiation (P=0.03)." (PMID 23599755, 2013). "Our study indicated that the expression of Klf4 mRNA was significantly correlated with vascular invasion and poor tumor differentiation." (PMID 23599755, 2013). "A positive and significant correlation of decreased Klf4 expression with tumor grade has been previously reported." (PMID 23451207, 2013). "In summary, here we present evidence that miR-10a, through a complex regulatory network involving the transcription factor Klf4, can contribute to tumor formation in female mice." (PMID 24204315, 2013). "The present study was the first to investigate the expression and potential tumor suppressive role of KLF4 in human ccRCC pathogenesis." (PMID 23861801, 2013). "Our data suggest that KLF4 acts as a tumor suppressor in HCC cells, in part by suppressing SLUG transcription." (PMID 22937066, 2012). "Ectopic Klf4 expression in HCC cells suppresses mesenchymal characteristics, cell migration and invasion, as well as tumor formation and lung colonization in vivo, whereas Klf4 knockdown enhanced mesenchymal features and cell migration in HCC cells." (PMID 22937066, 2012). "Similar to the findings in other types of cancers, our data suggested a possible role of KLF4 as a tumor suppressor in HCC." (PMID 22937066, 2012). "Hypoxia-exposure resulted in an up-regulation of c-Myc and OCT3/4 and a down-regulation of KLF4 mRNAs, suggesting their involvement in the tumour formation and angiogenesis." (PMID 23185562, 2012). "KLF4 was previously shown to play a crucial role in early development by regulating cell differentiation, tumor suppression, and steam cells." (PMID 22590687, 2012). "Using in vitro and in vivo functional analyses, we show that Klf4 acts as a tumor suppressor in HCC." (PMID 22937066, 2012). "Consistent with potential tumor suppressor activity, the over-expression of KLF4 reduced in vitro and in vivo tumorigenecity of colonic and gastric cancer cells." (PMID 22937066, 2012). "Immunostaining of tumor sections with an anti-Ki-67 antibody demonstrated fewer Ki-67-positive cells in Klf4-expressing tumor cells (34.53±2.815%) relative to controls (48.52±2.710%)." (PMID 22937066, 2012). "In summary, our data demonstrate that KLF4 acts as a tumor suppressor in HCC, at least in part by repressing SLUG expression." (PMID 22937066, 2012). "KLF4 transcription factor can function as a tumor suppressor and is down-regulated in various human cancer types such as gastric and colorectal cancer." (PMID 21978458, 2011). "In accordance, KLF4 is a putative tumor suppressor in B-cell malignancies, whereas KLF5 confers drug resistance to acute lymphoblastic leukemia by promoting survivin expression." (PMID 20119532, 2009). "Although these observations clearly define Klf4 as a tumor suppressor, it can also function as an oncogene." (PMID 20514221, 2009). "The tumor burden in Klf4+/-/ApcMin/+ mice was significantly increased compared to the ApcMin/+ mice." (PMID 20514221, 2009). "Specifically, miR‐206 targets and reduces KLF4 expression, thereby augmenting the production of M1‐associated markers, including CCL2, and promoting CCR2‐dependent recruitment of CTLs to the TME, ultimately impeding tumor initiation." (PMID 41532367, 2026).
tumor (continued). "KLF4 is recognized as a pivotal “bridge” molecule linking the immune system and tumor immunity." (PMID 41532367, 2026). "Future research directions should prioritize targeting KLF4 to reprogram TAMs from a tumor‐promoting M2 phenotype to a tumor‐suppressing M1 phenotype, which could pave the way for novel cancer treatments." (PMID 41532367, 2026). "Modulating KLF4 activity—whether by enhancing tumor‐suppressive functions or dampening oncogenic signaling—could reprogram the TME toward an anti‐tumor state." (PMID 41532367, 2026). "Overall, however, KLF4 tends to act as a tumor suppressor, functioning as a key anti‐cancer force." (PMID 41532367, 2026). "Inhibition of KLF4 could suppress CSCs self‐renewal and cell migration, impeding tumor growth and metastasis." (PMID 41532367, 2026). "In GC, KLF4 is consistently characterized as a tumor suppressor." (PMID 41532367, 2026). "Similarly, in glioblastoma, tumor‐derived kynurenine activates the AHR/KLF4/SOCS2/TRAF6 axis in TAMs, driving the expression of M2‐associated genes." (PMID 41532367, 2026). "Even so, it is still imperative to emphasize that inappropriate modulation of KLF4 activity could lead to severe adverse effects, such as promoting tumor growth or impairing normal cellular function." (PMID 41532367, 2026). "Through the MIF signaling axis, KLF4‐expressing CAFs promote immunosuppression and tumor invasion." (PMID 41532367, 2026). "Furthermore, elevated KLF4 expression exerts context‐dependent effects, either facilitating or limiting the infiltration of immune cells into tumor tissue." (PMID 41532367, 2026). "Exploring strategies to harness KLF4's therapeutic potential while minimizing adverse reactions is needed, which could focus on developing targeted drug delivery systems to enhance tumor‐specific drug accumulation." (PMID 41532367, 2026). "An intriguing hypothesis is that specific circRNA/miRNA axes modulate the tumor-promoting or -suppressive functions of KLF4 during specific disease stages." (PMID 40863723, 2025). "Targeting ACTL6A may therefore reactivate silenced tumor-suppressive gene networks through KLF4, offering a promising epigenetic therapeutic strategy for CRC." (PMID 40877226, 2025). "KLF4-driven fibrocyte differentiation also implicates this transcription factor in extracellular matrix remodeling and desmoplastic stroma formation, critical in tumor metastasis and drug resistance." (PMID 40552304, 2025). "It appears that KLF4, when regulated through the axes of the miR-7 family, miR-200b-3p, miR-29a, and miR-3182, plays a role of tumor promoter, favoring and accompanying the proliferation, invasiveness, and therapy resistance of tumors having different histological origins." (PMID 40863723, 2025). "Therefore, the presence of CDR1as maintains KLF4 expression, enhancing the tumor stem cell characteristics of HB." (PMID 41393242, 2025). "Additionally, this review will outline potential future research directions, emphasizing KLF4’s function in both normal immune cells and tumor immunity." (PMID 39995670, 2025). "These actions reveal the complex role of KLF4 in tumor immunity, warranting further investigation." (PMID 39995670, 2025). "KLF4 alterations in each given tumor type occur at a very low frequency." (PMID 40299916, 2025). "While KLF4 is regarded as a tumor suppressor in many human cancers, its role in DNA repair mechanisms remains unknown." (PMID 40699616, 2025). "However, their transfection experiments indicated that miR-10b enhances metastatic potential by targeting tumor-suppressor genes KLF4 and HOXD10." (PMID 40486882, 2025). "In summary, KLF4 has tumor suppressor activity in pediatric T-ALL, at least in part by inhibiting MAP2K7, which may be considered for therapeutic targeting." (PMID 40589762, 2025).
tumor (continued). "KLF4 upregulation in combination with the loss of marker expression, increased proliferation, migration, and ECM synthesis, as seen in our study in cells expanded in Pericyte medium, was reported in perivascular cells in response to tumor-secreted factors." (PMID 40558554, 2025). "Additionally, immunohistochemical experiments were performed on tissue chips to evaluate ADRB2 and KLF4 expression levels in tumor tissues of NSCLC, revealing markedly higher expression levels compared to adjacent normal tissues." (PMID 40276761, 2025). "In other words, KLF4 operates through different mechanisms in different tumor types." (PMID 40299916, 2025). "In addition, KLF4 is itself epigenetically modulated, a potential mechanism as a context-dependent tumor suppressor, adding another layer of complexity to KLF4 in epigenetic regulation." (PMID 40552304, 2025). "OTUD1 may inhibit the proliferation, migration, and invasion of NSCLC cells by deubiquitinating and stabilizing the tumor suppressors KLF4 and FHL1." (PMID 41050073, 2025). "In breast and colorectal cancers, KLF4 has been shown to interact with other key transcription factors like Sox2 and Oct4 to regulate the balance between self-renewal and differentiation, thereby influencing tumor progression and response to therapy." (PMID 40868290, 2025). "In addition to CD8+ T cells, macrophage content is significantly higher in the tumor tissues of HCC patients with high KLF4 expression compared to low KLF4 expression." (PMID 39995670, 2025). "These contradictory findings suggest that KLF4 may exhibit distinct roles depending on tissue-specific gene regulation, the tumor microenvironment, and interactions with other signaling pathways." (PMID 40299916, 2025). "KLF4 has both tumor suppressor and pro-oncogenic roles in carcinogenesis." (PMID 40589762, 2025). "The “Pathological Stage Plot” module of GEPIA2 was employed to determine whether KLF4 expression differs based on tumor pathological stage." (PMID 40299916, 2025). "Inhibit tumor growth and upregulate the expressions of PTEN and KLF4 in tumor tissues." (PMID 40672375, 2025). "Likewise, KLF4 can function as either a tumor suppressor or a pro-oncogene, depending on the regulation of cell cycle and signaling within an oncogenic environment." (PMID 40589762, 2025). "Moreover, miR-152 overexpression and KLF4 knockdown resulted in the smallest tumor volume and longest survival in nude mice." (PMID 40566589, 2025). "Additionally, adenosylmethionine decarboxylase 1 (Amd1) upregulates Sry-box transcription factor 2 (Sox2), Kruppel-like factor 4 (Klf4), and Nanog through Fto-mediated mRNA demethylation, maintaining tumor stemness." (PMID 41208876, 2025). "The topic of whether KLF4 acts as a tumor suppressor or a tumor promoter specifically in CRC is still controversial, since there is evidence supporting either one or the other function." (PMID 40863723, 2025). "Thus, KLF4 expression and immune cell infiltration levels were examined across various TCGA tumor types using TIMER, CIBERSORT, CIBERSORT-ABS, QUANTISEQ, XCELL, MCPCOUNTER, and EPIC algorithms." (PMID 40299916, 2025). "Overall, the data in this study further confirm that KLF4 is a tumor suppressor and proposes repair proteins that may be involved in the KLF4 regulatory pathway." (PMID 40699616, 2025). "This dual role is further complicated by the fact that different stages of a tumor may display different KLF4 epigenetic states modulating its functions." (PMID 40863723, 2025). "Moreover, the expression of KLF4 in HCC tissues is generally lower than in adjacent non-tumor tissues." (PMID 39995670, 2025).
tumor (continued). "Evidence also indicates that KLF4 functionsas a tumor suppressor in certain cancers." (PMID 39944803, 2024). "Our most exciting finding is the discovery in single-cell sequencing results that metastatic tumor endothelial cells have a significant senescent state that is driven by KLF4 and validated in human tissues with in vitro experiments, and confirmed by in vitro modeling based on existing studies." (PMID 38951874, 2024). "The results presented here identify the interaction between hepatocyte-derived plexin B2 and class IV semaphorins on tumour cells as a necessary inducer of KLF4-mediated epithelialization of liver metastases and lay a methodological framework to deepen our understanding of metastatic seeding." (PMID 39048831, 2024). "In this study, we demonstrate that KLF4 functions as a tumor suppressor in HCC." (PMID 39000273, 2024). "Fan S.H., Wang Y.Y., Wu Z.Y., Zhang Z.F., Lu J., Li M.Q., Shan Q.,Wu D.M., Sun C.H., Hu B., Zheng Y.L. AGPAT9 suppresses cellgrowth, invasion and metastasis by counteracting acidic tumor microenvironmentthrough KLF4/LASS2/V-ATPase signaling pathwayin breast cancer." (PMID 39944803, 2024). "While the use of all four factors (OKSM) can lead to adverse effects, two of the Yamanaka factors, c-Myc and Klf4, are known oncogenic factors and may promote tumor development." (PMID 38391956, 2024). "Cumulatively, these data support the role of plexin B2–semaphorin–KLF4 signalling in promoting liver seeding, and might explain the differential ability of distinct tumour cell subpopulations to successfully form hepatic metastases." (PMID 39048831, 2024). "The downregulation of GPX8 could increase the expression of the tumor stemness markers KLF4, OCT4, and CD133." (PMID 38607517, 2024). "There is increasing evidence describing KLF4 as a double effector in tumor development." (PMID 38794128, 2024). "The current knowledge points towards KLF4 as a tumor suppressor in both solid and hematological tumors, where the gene is silenced by means of a variety of mechanisms including DNA hypermethylation, interactions with miRNAs, histone modifications and others, described subsequently in the manuscript." (PMID 39135777, 2024). "These last evidences support the tumor promoting role of KLF4." (PMID 39135777, 2024). "Additionally, KLF4 inhibits the migration and invasion of tumor cells by suppressing biological enzymes like TIMP-1 and TIMP-2." (PMID 39000273, 2024). "We therefore hypothesized that reactivation of KLF4 at secondary sites might promote epithelialization of tumour cells through reversion of EMT, which is thought to be essential for successful metastatic outgrowth of several carcinomas." (PMID 39048831, 2024). "However, KLF4 levels increased with tumor size and with the presence of nodal metastases compared to the ones without metastatic spread." (PMID 39135777, 2024). "Moreover, expression of Klf4 as well as its predicted target genes was increased in tumour cells in Plxnb2-OE livers, as well as in AKPS organoids treated with rmPlexin B2." (PMID 39048831, 2024). "In the context of HCC, KLF4 has been identified as a tumor suppressor." (PMID 39000273, 2024). "Additionally, in vivo experiments further confirmed that RICTOR knockdown effectively negated the impact of KLF4 silencing, as evident from weekly tumor volume measurements and final tumor weight determinations." (PMID 39000273, 2024). "KLF4 is a tumor suppressor, and its downregulation is related to class I histone deacetylases, lung inflammation in conjunction with K-ras activation, tumorigenesis, the modulation of cell proliferation, cell growth, epithelial–mesenchymal transition, invasion, and metastases." (PMID 36661515, 2023). "In addition, in multivariate analysis, only three of 8 prognostic factors remained independent, including KLF4 expression, tumor differentiation, and TNM stage, remained independent prognostic factors." (PMID 36936440, 2023).